EGF (epidermal growth factor)
Diseases named in the same sentence as EGF in open-access papers (continued):
Sharing a sentence is not in itself a finding about the gene and the disease.
Cirrhosis (22 papers, 2010 to 2024). A chronic disorder of the liver in which liver tissue becomes scarred and is partially replaced by regenerative nodules and fibrotic tissue resulting in loss of liver function. "A SNP in the epidermal growth factor (EGF) gene (rs4444903) was associated with an elevated risk of HCC in patients with cirrhosis." (PMID 33255794, 2020). "EGF expression in the liver increases during cirrhosis, and the level of EGF mRNA expression is associated with poor survival of cirrhotic patients." (PMID 28691020, 2017). "However, a recent study reported an association between carriage of the EGF G allele and cirrhosis in 62 subjects with chronic HBV infection." (PMID 25504078, 2014). "Whether higher EGF levels are associated with a greater risk of developing cirrhosis and a shorter time taken to develop cirrhosis were aspects not addressed by this study." (PMID 22470194, 2012). "In the liver, EGF is upregulated in a rat model of liver fibrogenesis and in human cirrhotic liver tissues, and a polymorphism in the human EGF gene that leads to increased EGF expression is associated with increased fibrosis and cirrhosis progression in patients with chronic hepatitis C." (PMID 38488009, 2024). "A prior study additionally demonstrated a correlation between greater fibrosis and cirrhosis progression and a variation in the human EGF gene that results in higher EGF production." (PMID 38560050, 2024). "In this study, we aimed to investigate the contribution of previously implicated genetic risk factors (PNPLA3, TM6SF2, EGF, MTHFR) for the development of cirrhosis and HCC in the Croatian population." (PMID 34640639, 2021). "Another study showed a significant increase in EGF expression in rats during the course of cirrhosis development." (PMID 26062544, 2015). "Our findings extend the results of these studies by identifying a role for the EGF locus independently or in concert with two additional SNPs in not only the development of HCC but also the progression of HCV-related cirrhosis." (PMID 25504078, 2014). "We found significant associations between EGF, IL28B, and PNPLA3 genotypes and the risk of clinical deterioration in patients with HCV-related cirrhosis." (PMID 25504078, 2014). "Our findings suggest that the EGF 61*A/G polymorphism is a genetic susceptibility factor for HCC only in the background of chronic HBV infection and/or cirrhosis." (PMID 22403631, 2012). "The transcription of EGF was shown to be extremely low in control livers but was highly elevated in cirrhotic livers of human patients, and EGF expression was increased significantly during the course of cirrhosis development in a rat model." (PMID 20618941, 2010). "Although it was reported that the expression of EGF and its receptor increase in cirrhosis and in viral liver disease, we found that levels of EGF-R were comparable in HBV, HCV, bilharziasis and the controls." (PMID 27942306, 2010). "Furthermore, EGF expression decreased significantly during chronic liver injury, whereas it has been shown to increase during development of human cirrhosis." (PMID 20618941, 2010). "We also conducted analyses restricted to those with Child-Pugh Class A cirrhosis, and found that EGF non-AA genotype was associated with the risk of clinical deterioration in Child-Pugh Class A subjects (age, sex, race-adjusted HR = 3.30; 95%CI 1.46–7.35; p = 0.004)." (PMID 25504078, 2014). "Moreover, EGF expression, as assessed in a gene expression signature in non-tumoral liver tissue, is associated with poor survival in HCC patients after resection and with progression to advanced cirrhosis, HCC development and poor survival in HCV-related early-stage cirrhosis." (PMID 25504078, 2014). "We genotyped SNPs in EGF, PNPLA3, and IL28B from liver tissue from 169 patients with biopsy-proven HCV cirrhosis." (PMID 25504078, 2014).
Cirrhosis (continued). "In the current study, we exposed mice to CCl4 to create fibrosis, cirrhosis, and HCC and assessed histopathology, EGF expression, and HSC populations." (PMID 20618941, 2010). "Three original studies were identified investigating the rs4444903 SNP of the EGF gene, two studying HCC8, 9(578 patients in total) and one studying fibrosis, with a variety of comparison groups (including HCV‐infected and HCV‐related cirrhosis patients)." (PMID 29397014, 2018). "However, no study has evaluated the influence of IL28B, EGF, and PNPLA3 genotypes on the natural history of HCV-related cirrhosis or examined these SNPs in the same population." (PMID 25504078, 2014).
esophageal cancer (21 papers, 1995 to 2025). A primary or metastatic malignant neoplasm involving the esophagus. "Moreover, the EGF-EGFR gene-gene interaction was shown to increase the susceptibility to esophageal cancer." (PMID 36092955, 2022). "Maspin has an inhibitory role in esophageal cancer by suppressing epidermal growth factor (EGF)-induced EMT." (PMID 40606680, 2025). "In esophageal cancer cells, loss of TGF-β was shown to activate ADAMTS1-mediated EGF-dependent invasion." (PMID 39333870, 2024). "The epidermal growth factor (EGF) and its receptor (EGFR) gene-gene interactions were shown to increase the susceptibility to esophageal cancer." (PMID 36092955, 2022). "KYSE520, an EGFR-amplified esophageal cancer cell line, showed loss of GAB1 Y659 phosphorylation with SHP099 treatment under conditions of EGF stimulation." (PMID 33755016, 2021). "The reactivity of esophageal cancer cells to recombined EGF was strikingly attenuated after genistein treatment (8 μM) for 9 d, compared with Eca-109 cells treated with recombined EGF alone (P<0.05)." (PMID 32276266, 2020). "Because both EGF and AREG have been implicated in progression of esophageal cancer, it was of interest to examine the involvement of SPHK1." (PMID 21936950, 2011). "Similar with CMTM3, CMTM7 enhanced Rab5 activation to attenuate EGF signaling in esophageal cancer." (PMID 39948411, 2025). "In conclusion, enhancing EGF signaling might also represent a promising therapeutic avenue for esophageal cancers." (PMID 40909948, 2025). "Moreover, epidermal growth factor (EGF) has also been reported to inhibit tumor cell proliferation in esophageal cancers via STAT1 activation, paralleling the signaling of IFN-γ that induces apoptosis in esophageal tumor cells." (PMID 40909948, 2025). "Interestingly, the findings that nuclear translocation of SHCBP1 by EGF was also observed in cancer cell lines derived from liver, breast, and esophageal carcinomas, suggesting a possible generalizability of this biological event among different types of cancers." (PMID 30177836, 2019). "In addition, PAR2 activation promotes the reversal of epidermal growth factor (EGF) and the release of TGF-α, induces tumor angiogenesis, and mediates the proliferation of gastric, colon, and esophageal cancer cells." (PMID 38172304, 2024).
Parkinson disease (21 papers, 2010 to 2025). A progressive degenerative disorder of the central nervous system characterized by loss of dopamine producing neurons in the substantia nigra and the presence of Lewy bodies in the substantia nigra and locus coeruleus. "Serum EGF levels have been found to be associated with a variety of diseases, including Parkinson’s disease, several tumors and inflammatory diseases." (PMID 32477838, 2020). "EGF was found to be negatively correlated with cognitive disfunction in Parkinson’s disease, suggesting a neuroprotective effect." (PMID 39595087, 2024). "In patients with Parkinson's Disease, SVZ proliferation is markedly reduced, a side effect of loss of dopaminergic innervations related to the stimulatory activity of dopamine on EGF and CNTF secretion by SVZ NSCs." (PMID 22394166, 2012). "In a model of Parkinson's disease, the combined application of growth factors such as epidermal growth factor and fibroblast growth factor 2 was sufficient to enhance migration of neuroblasts to the striatum; however it did not result in neuronal maturation." (PMID 20836877, 2010). "It is worth noting, that EGF is utilized in clinical practice, e.g., in Parkinson’s disease or diabetic foot ulcers; it then might be a very attractive therapeutic option in various neuropsychiatric conditions." (PMID 38004423, 2023). "Supplement of EGF to Parkinson disease (PD) model rat prevented the dopaminergic neurodegeneration." (PMID 29038492, 2017). "Moreover, plasma EGF may be a biomarker for progression to MCI in Parkinson’s patients, as it was correlated with cognitive functioning at baseline and showed predictive capacity over time." (PMID 24495355, 2014). "This factor can prevent dopaminergic neurodegeneration in the animal models of Parkinson’s disease, and this GDNF action is mimicked by EGF." (PMID 36830741, 2023). "In vivo administration of EGF, HB-EGF, or neuroegulin-1 elevates the concentrations of dopamine and its metabolite, 4-dihydroxyphenylacetic acid (DOPAC), in the striatum of Parkinson’s model animals as well as in normal rats." (PMID 36830741, 2023). "In MDA MB-231, pathway analysis also showed the involvement of proteins in glycolysis, blood coagulation, EGF signaling pathway, FGF signaling pathway, and Huntington and Parkinson disease-related pathways, along with those present in MCF-7." (PMID 37900279, 2023). "Infusion of epidermal growth factor (EGF) and fibroblast growth factor 2 in a Parkinson's disease animal model elevated neural stem cell proliferation in the SVZ and enhancement of dopaminergic neurogenesis in the olfactory bulb." (PMID 31788470, 2019). "Many signaling pathways including 14-3-3 mediated, neuregulin, semaphorin, ephrin, gap-junction, axonal guidance, as well as different growth factor signaling like EGF/EGFR, FGF, and NGF, were found enriched in Parkinson's disease pathology." (PMID 24688734, 2013). "Although few studies have proven the decline in EGF in normal aging, the level of EGF decreases in the early stage of Parkinson’s disease, which is related to the nonmotor symptoms of PD patients." (PMID 38649851, 2024).
chronic kidney disease (20 papers, 2018 to 2026). Impairment of the renal function secondary to chronic kidney damage persisting for three or more months. "As we mentioned, urinary EGF is associated with eGFR decline in various other chronic kidney diseases besides ADPKD." (PMID 36914219, 2023). "Chronic kidney disease is associated with reduced urine EGF, and decreased urine EGF levels predicted response to steroid therapy in primary glomerulonephritis." (PMID 35271583, 2022). "Our recent work has shown that EGF is inversely correlated with IFTA, that is, increased urinary excretion of EGF was associated with a lower degree of IFTA in renal biopsies obtained from adults with primary nephrotic syndrome or chronic kidney disease from a variety of causes." (PMID 32280839, 2020). "In this study, we hypothesized that single nucleotide polymorphisms (SNPs) in EGF or its receptor genes might have an association with end-stage renal disease (ESRD) or acute renal allograft rejection (AR) in a Korean population." (PMID 31906817, 2020). "Likewise, in patients with chronic kidney disease lower urinary EGF excretion was associated with a steeper slope of kidney function decline and worse renal outcome (defined as the incidence of end-stage kidney disease and/or a 40% reduction in eGFR), in both adults [28 and 29] as well as children." (PMID 36914219, 2023). "These chronic kidney diseases have different underlying pathophysiology (with respect to the degree of inflammation, proliferation and fibrosis), which itself may have an effect on urinary EGF excretion." (PMID 36914219, 2023). "Urinary epidermal growth factor (uEGF) and clusterin (uCLU) are emerging biomarkers in chronic kidney disease (CKD), but rigorous analytical validation is required before clinical implementation." (PMID 42123423, 2026). "Urinary MCP-1, a chemotactic factor for monocytes, reflects inflammation and macrophage activation within the kidneys, while urinary EGF, a marker for tubular cell mass, indicates renal function and progression in chronic kidney disease (CKD)." (PMID 39200287, 2024). "It is noteworthy to mention that EGF levels increase in the serum of patients with DN at all stages of chronic kidney disease (CKD) compared to healthy controls." (PMID 35008447, 2021). "Further, the addition of EGF measures to demographic and clinical features improved the ability to predict progression of chronic kidney disease." (PMID 32280839, 2020). "Reduced concentrations of EGF in the urine have been previously observed in diabetes nephropathy, IgA nephropathy, adult polycystic kidney disease, and children with chronic renal failure." (PMID 30677083, 2019). "A role for EGF in predicting outcome in chronic kidney diseases is being increasingly recognized, but there is limited data in DKD." (PMID 30241508, 2018). "They suggested urinary EGF as a prognostic biomarker for progression of chronic kidney disease." (PMID 31906817, 2020). "Urinary EGF has recently been identified as a promising biomarker of chronic kidney disease (CKD) progression in adults with glomerular disease." (PMID 39587192, 2024). "In the case of drug-induced AKI with progression to end-stage renal disease (ESRD), the urinary EGF level continued to decrease until the patient was discharged, and the serum creatinine level remained high." (PMID 38732362, 2024). "EGF has a well-understood action via the activation of the EGF receptor which is linked to inflammatory responses in terms of wound healing in mouse model keratinocytes, cellular proliferation, chronic kidney disease and tumorigenesis in humans, all of which are negative outcomes of ageing." (PMID 33723630, 2021). "In this study, we investigated the potential of EGF, ZFP36, and PAG1 as biomarkers for chronic kidney disease (CKD)." (PMID 37988198, 2023).
oral squamous cell carcinoma (20 papers, 2010 to 2025). "However, the underlying signaling mechanisms for EGF-induced migration of oral squamous cell carcinoma (OSCC) remain to be elucidated." (PMID 32174831, 2020). "For example, recombinant epidermal growth factor (EGF) treatment can promote the uptake of oral squamous cell carcinoma (OSCC) cell-derived exosomes into the OSCC cells." (PMID 38992695, 2024). "Dias and colleagues found that reducing metallothionein 2A levels using siRNA lowered MMP-9 and EGF protein levels, leading to decreased proliferation, migration, and invasion in human oral squamous cell carcinoma cells." (PMID 38374934, 2024). "A significant increase in serum EGF levels in patients with oral squamous cell carcinoma (OSCC), papillary thyroid cancer patients and in lung tumour patients has been described earlier." (PMID 34115785, 2021). "The intracellular signaling pathways controlling epidermal growth factor (EGF)-induced amphiregulin (AREG) expression were examined in three oral squamous cell carcinoma (OSCC) cell lines." (PMID 27669890, 2016). "Signaling via epidermal growth factor and its receptor is an essential oncogenic pathway in HNSCC and oral squamous cell carcinoma (OSCC), and this signaling pathway enhanced AKT activation and upregulated C/EBPβ expression in OSCC." (PMID 34201353, 2021). "In this study, we explored the role of epidermal growth factor (EGF) in orchestrating Warburg effect, the epithelial-mesenchymal transition (EMT) process, and the acquisition of cancer stem-like cell properties in human oral squamous cell carcinoma (OSCC) cells." (PMID 27926487, 2017). "For example, in an oral squamous cell carcinoma model, the combination of TGF-β1 and EGF, but not either alone, induced cell scattering activity." (PMID 25493076, 2014).
psoriasis (19 papers, 2006 to 2025). An autoimmune condition characterized by red, well-delineated plaques with silvery scales that are usually on the extensor surfaces and scalp. "Previous studies have shown that the status of epidermal proliferation changes with thyroid disease, and thyroid hormones are able to induce the production of epidermal growth factor (EGF), whose persistence could be associated with the hyperproliferative state of psoriasis." (PMID 37598033, 2024). "We found that the transcriptional response to IFN-γ is profoundly altered in the presence of EGF on a genome-wide level in keratinocytes and correlated with gene expression findings from skin samples collected from individuals with psoriasis." (PMID 39924511, 2025). "Growth factors and their receptors such as VEGFA, EGF, and EGFR were also inextricably linked with psoriasis." (PMID 35265149, 2022). "For example, EGFR and its ligands are overexpressed in patients with psoriasis, and increased serum EGF concentrations correlate with the severity of psoriasis." (PMID 33096942, 2020). "Based on our in vitro results, we further investigated whether EGF may modify IFN-γ target gene expression in vivo using RNA-seq data of skin samples from individuals with psoriasis." (PMID 39924511, 2025). "At each step of the psoriasis molecular pathway, different inflammatory cytokines such as IL-6, IL-17, IL-22, and IL-23 are triggered, on the other side, growth factors such as EGF, VEGF, KGF, and IGF-1, which underscores the central role which predominantly drives epidermal hyperplasia." (PMID 33849555, 2021). "Similarly, in other inflammatory skin conditions such as psoriasis, where the expression of growth factors, including EGF, is upregulated, similar mechanisms involving the internalization of barrier proteins may occur within the lesional skin." (PMID 40266031, 2025). "The receptors of T3 are expressed in epidermal keratinocytes and may have a role in the proliferation of these cells by increasing epidermal growth factor (EGF); the EGF receptors expression is increased in psoriasis that may highlight the effect of thyroid hormones in the pathogenesis of psoriasis." (PMID 24288511, 2013). "Bearing in mind that this interleukin actssynergistically with IL-1 and tumor necrosis factor alpha(TNF-α) further supports the hypothesis that IL-6 maycontribute via its receptor action to epidermal growth factor(EGF) function in modulating cell hyperproliferation in psoriasis." (PMID 16864908, 2006). "When treating these four subpopulations as receptor sources, subsequent pathway analysis indicated that the communication networks in psoriasis encompassed several key immune and signaling pathways, including IL - 17, CXCL, midkine (MK), IL - 6, NOTCH, EGF, and MHC-II." (PMID 40959079, 2025). "In summary, our findings suggest that EGF may significantly dampen the IFN-γ-induced transcriptome in keratinocytes, including genes involved in leukocyte trafficking, antigen presentation, and tissue inflammation upregulated in autoimmune diseases like psoriasis and by EGFR inhibitors." (PMID 39924511, 2025). "The significant induction of TNF-α increased IL-6, IL-8, EGF, HGF, TGF-α, epiregulin, and amphiregulin, but the increase in these cytokines and growth factors were not different among normal skin, uninvolved, and involved psoriasis." (PMID 20161853, 2009).